RNU6-721P (RNA, U6 small nuclear 721, pseudogene)
Gene: Small nuclear RNA gene on chromosome 18 (15,320,840 to 15,320,944, reverse strand). Ensembl gene ENSG00000222087.
Homologues: Orthologues: chimpanzee U6 (98% identical), macaque U6 (90% identical), dog U6 (65% identical), rabbit U6 (64% identical), rabbit U6 (61% identical), pig U6 (60% identical). Paralogues in human: RNU6-1132P (98% identical), RNU6-614P (98% identical), RNU6-1293P (97% identical), RNU6-156P (97% identical), U6 (97% identical), RNU6-458P (96% identical), U6 (96% identical), RNU6-1207P (91% identical), RNU6-811P (91% identical), RNU6-978P (91% identical), RNU6-452P (87% identical), RNU6-666P (86% identical), and 1286 more.